RNY4P36 (RNY4 pseudogene 36)
Gene: Miscellaneous RNA gene on chromosome 17 (76,703,632 to 76,703,727, reverse strand). Ensembl gene ENSG00000212418.
Homologues: Orthologues: chimpanzee Y_RNA (98% identical), macaque Y_RNA (95% identical). Paralogues in human: RNY4 (88% identical), RNY4P19 (88% identical), RNY4P7 (88% identical), RNY4P37 (86% identical), RNY4P6 (86% identical), Y_RNA (86% identical), RNY4P3 (85% identical), Y_RNA (85% identical), RNY4P10 (84% identical), RNY4P13 (84% identical), Y_RNA (84% identical), RNY4P14 (83% identical), and 89 more.